VMA12 (vacuolar ATPase assembly factor VMA12)
Description:
Accessory component of the proton-transporting vacuolar (V)- ATPase protein pump involved in intracellular iron homeostasis. In aerobic conditions, required for intracellular iron homeostasis, thus triggering the activity of Fe(2+) prolyl hydroxylase (PHD) enzymes, and leading to HIF1A hydroxylation and subsequent proteasomal degradation. Necessary for endolysosomal acidification and lysosomal degradation. May be involved in Golgi homeostasis. Binds 20(S)-hydroxycholesterol (20(S)-OHC) (By similarity).
Synonyms: C17orf32; TMEM199; VPH2; MGC45714; CDG2P
Tractability: Antibody: UniProt predicts a signal peptide or a membrane-spanning region. PROTAC: ubiquitination databases record sites on it.
Gene: Protein-coding gene on chromosome 17 (28,357,642 to 28,363,683, forward strand). Ensembl gene ENSG00000244045.
Subcellular location: Cytoplasmic vesicle, COPI-coated vesicle membrane; Endoplasmic reticulum-Golgi intermediate compartment membrane; Endoplasmic reticulum membrane
Gene Ontology:
Molecular function: protein binding; oxysterol binding
Biological process: cellular response to increased oxygen levels; intracellular iron ion homeostasis; lysosomal lumen acidification; lysosomal protein catabolic process; vacuolar proton-transporting V-type ATPase complex assembly
Cellular component: COPI-coated vesicle membrane; endoplasmic reticulum; endoplasmic reticulum membrane; endoplasmic reticulum-Golgi intermediate compartment membrane; vacuolar proton-transporting V-type ATPase complex; endomembrane system; lysosome
Genetic constraint (gnomAD): Loss-of-function variants: 24 observed, 24.56 expected, observed/expected ratio (o/e) 0.98, 90% interval 0.71 to 1.37. The upper end of that interval is the gene's LOEUF score, 1.37, which puts it in group 5 of 6, group 1 being the genes least tolerant of losing a copy. Missense variants: 287 observed, 283.52 expected, observed/expected ratio (o/e) 1.01, 90% interval 0.92 to 1.12. Synonymous variants: 138 observed, 119.98 expected, observed/expected ratio (o/e) 1.15, 90% interval 1 to 1.33.
Homologues: Orthologues: chimpanzee TMEM199 (100% identical), macaque TMEM199 (98% identical), pig VMA12 (92% identical), rabbit VMA12 (91% identical), rat Tmem199 (91% identical), dog VMA12 (90% identical), mouse Tmem199 (89% identical), guinea pig VMA12 (88% identical), tropical clawed frog tmem199 (56% identical), zebrafish tmem199 (46% identical), Drosophila melanogaster CG7071 (28% identical), Caenorhabditis elegans F09E5.11 (19% identical).
Diseases named in the same sentence as VMA12 in open-access papers:
VMA12 is named in the same sentence as 27 diseases in open-access papers, as found by Europe PMC text mining. Sharing a sentence is not in itself a finding about the gene and the disease.
VMA12 shares sentences with these, for which no sentence is quoted: liver disease (5 papers); steatosis (3); cancer (2); Cirrhosis (2); Hepatic steatosis (2); hepatopathy (2); Immunodeficiency (2); tumor (2); autosomal recessive inherited disease (1); breast carcinoma (1); Cognitive impairment (1); congenital disorder of glycosylation (1); copper metabolism disorder (1); cryptogenic cirrhosis (1); cutis laxa (1); disorder of glycosylation (1); disseminated candidiasis (1); epilepsy (1); hair loss (1); hepatoma (1); Hypercholesterolemia (1); hyperlipidemia (1); infection (1); liver fibrosis (1); sensorineural deafness (1); Strabismus (1); viral infections (1).